LOX (lysyl oxidase)
Diseases named in the same sentence as LOX in open-access papers (continued):
Sharing a sentence is not in itself a finding about the gene and the disease.
cerebral aneurysm (2 papers, 2019 to 2020). "A single nucleotide polymorphism of LOXL2 has been associated with cerebral aneurysms, suggesting that the inhibition of LOX/LOXLs could be a key event in the pathophysiology of this disease." (PMID 31615160, 2019). "In cerebral aneurysms, prominent degradation of the extracellular matrix and the vascular wall involves reduced LOX expression and elevated IL-1β that, in aortic smooth muscle cells, was confirmed to activate NF-κβ, the inhibition of which restored LOX levels." (PMID 32708046, 2020). "A reduction of vascular LOX expression has also been described in patients with cerebral aneurysm and in experimental models of this disease, an effect associated with the high vascular levels of interleukin-1β and the activation of NFĸB signaling characteristics of this disorder." (PMID 31615160, 2019).
chondrosarcoma (2 papers, 2021 to 2022). A malignant cartilaginous matrix-producing mesenchymal neoplasm arising from the bone and soft tissue. "A positive correlation observed between NGF and LOX staining intensity of human chondrosarcoma tissue (r2 = 0.534) indicates that the levels of these proteins (NGF and LOX) are associated with the progression of chondrosarcoma disease." (PMID 34815382, 2021). "Our study is the first to describe an association between levels of LOX expression and tumor stage in chondrosarcoma tissue specimens." (PMID 34815382, 2021). "Our investigation has found that levels of NGF and LOX expression are positively correlated with tumor staging in patients with chondrosarcoma." (PMID 34815382, 2021). "In conclusion, our study has identified that NGF promotes LOX-dependent migratory and invasive activities in human chondrosarcoma cells by suppressing miR-149-5p synthesis via the PI3K, Akt, and mTOR signaling cascades." (PMID 34815382, 2021). "Our data indicate that endogenous NGF augments LOX-dependent lung metastasis of chondrosarcoma in mice." (PMID 34815382, 2021). "Our in vitro and in vivo evidence suggests that NGF facilitates LOX-dependent chondrosarcoma metastasis." (PMID 34815382, 2021). "We also confirmed that NGF facilitates LOX-dependent chondrosarcoma cell migration and metastasis by suppressing miR-149-5p synthesis via PI3K, Akt, and mTOR signaling." (PMID 34815382, 2021). "PI3K inhibitor treatment antagonized NGF-facilitated Akt phosphorylation, indicating that the PI3K/Akt signaling pathway controls NGF-enhanced LOX synthesis, as well as chondrosarcoma cell migration and invasion." (PMID 34815382, 2021). "miR-149-5p expression was negatively correlated with LOX expression, as well as with the migratory and invasive activities of chondrosarcoma cells." (PMID 34815382, 2021). "Our study results here show that NGF promotes phosphorylation of PI3K and Akt, while PI3K and Akt pharmacological inhibitors suppress NGF-induced promotion of LOX expression, chondrosarcoma cell migration, and invasion." (PMID 34815382, 2021). "PI3K and Akt inhibitors also inhibited NGF-promoted phosphorylation of mTOR, indicating that PI3K/Akt-dependent mTOR activation mediates NGF-facilitated promotion of LOX synthesis and chondrosarcoma cell motility." (PMID 34815382, 2021). "Stimulation of cells with NGF enhanced LOX mRNA and protein expression, implying that LOX is critical to NGF-promoted chondrosarcoma cell migration and invasion." (PMID 34815382, 2021). "IHC data revealed higher levels of LOX expression in patients with higher-grade chondrosarcoma than in those with lower-grade disease; the levels of LOX expression were reflected by tumor stage." (PMID 34815382, 2021). "We enhanced miR-149-5p levels in chondrosarcoma cells by transfecting them with a specific miR-149-5p mimic, which markedly reduced LOX synthesis and the migratory capacity of the cells." (PMID 34815382, 2021). "Notably, levels of NGF and LOX expression correlated with tumor stage in human chondrosarcoma samples." (PMID 34815382, 2021). "In this study, we investigated LOX expression in patients with chondrosarcoma." (PMID 34815382, 2021). "LOX is therefore a promising molecular targeting for treating chondrosarcoma metastasis." (PMID 34815382, 2021). "Finally, we examined potential candidate miRNAs that could affect LOX mRNA expression in chondrosarcoma cell lines, and the potential role of NGF in this process." (PMID 34815382, 2021). "We report that NGF facilitates lysyl oxidase (LOX)-dependent cellular migration and invasion in human chondrosarcoma cells, and that NGF overexpression enhances lung metastasis in a mouse model of chondrosarcoma." (PMID 34815382, 2021). "Immunohistochemistry (IHC) results revealed significant increases in the levels of LOX expression in the JJ012/NGF orthotopic model, confirming that NGF facilitates the metastasis of chondrosarcoma to the mouse lung." (PMID 34815382, 2021).
chondrosarcoma (continued). "We also sought to determine whether LOX mediates NGF-induced migration and invasion abilities of chondrosarcoma cells, and whether this process is regulated by PI3K, Akt, and mTOR signaling." (PMID 34815382, 2021). "Treating chondrosarcoma with PI3K, Akt, and mTOR inhibitors reversed NGF-promoted inhibition of miR-149-5p expression, which suggests that NGF may increase LOX expression and chondrosarcoma metastasis by inhibiting miR-149-5p synthesis via the PI3K, Akt, and mTOR signaling cascades." (PMID 34815382, 2021).
clubfoot (2 papers, 2022). The most common congenital deformation of the foot, occurring in 1 of 1,000 live births. "In clubfoot patients, LOX protein and LOX-mediated crosslink density levels are both higher in the contracted tendons as compared to the non-contracted tendons." (PMID 35992359, 2022). "In addition to poor tendon healing, abnormal LOX-mediated collagen crosslinking has been implicated in heritable connective tissue disorders and birth abnormalities that affect tendon, including EDS, clubfoot, and Menkes disease." (PMID 35992359, 2022). "We observed a significant increase in the positivity of LOX and LOXL2 (two of the main LOXs) in the contracted tissue (M-side) of the relapsed clubfoot in comparison with non-contracted tissue by IHC." (PMID 35292718, 2022).
colorectal adenocarcinoma (2 papers, 2021). The most common type of colorectal carcinoma. "TGF-β1 mediated LOX increase in fibroblasts and colorectal adenocarcinoma can be blocked by inhibitors of PI3K, p38-MAPK, JNK and ERK1/2, respectively." (PMID 33513979, 2021).
coronary artery disease (2 papers, 2021 to 2022). "In our study, we found four genes with single nucleotide variants (SNVs) associated with coronary artery disease—HNF1A, LOX, SMAD3, and SMARCA4, and one gene, EBF1, with a SNV associated with carotid intima media thickness for the gens in significant modules." (PMID 35925965, 2022).
cutis laxa (2 papers, 2019 to 2024). Cutis laxa (CL) is an inherited or acquired connective tissue disorder characterized by wrinkled, redundant and sagging inelastic skin associated with skeletal and developmental anomalies and, in some cases, with severe systemic involvement. "Moreover, we were able to show that familial pathogenic variants in EMILIN1 cause cutis laxa and bone fragility by affecting the deposition of fibulin-4 and the activity of lysyl oxidase (LOX), a vital enzyme required for the stable formation of elastic fibers and the collagen network." (PMID 39639116, 2024). "The main clinical features, including cutis laxa, bony exostoses, and bladder diverticula are attributed to a decreased activity of lysyl oxidase (LOX), a cupro-enzyme involved in collagen crosslinking." (PMID 31336972, 2019).
diabetic nephropathy (2 papers, 2019 to 2025). "This establishes a critical pathogenic role for endothelial-derived LOX and LOXL2 in promoting mesangial cell injury, oxidative stress, and fibrosis, key features of diabetic nephropathy." (PMID 41355449, 2025). "This work establishes endothelial LOX and LOXL2 as lynchpins within the dysregulated signaling network governing glomerular injury in diabetic nephropathy." (PMID 41355449, 2025).
dilated cardiomyopathy (2 papers, 2020 to 2025). Cardiomyopathy which is characterized by dilation and contractile dysfunction of the left and right ventricles. "“Lysyl oxidase” is interconnected with terms such as “dilated cardiomyopathy”, “tumor microenvironment”, and those related to fibrosis, vividly demonstrating LOX’s diverse functions across various medical conditions." (PMID 40661776, 2025). "In a mice model of dilated cardiomyopathy (DCM) after autoimmune myocarditis, serum and cardiac sPLA2-IIA protein expression were found to be increased, together with elevated cardiac levels of the cross-linking enzyme lysyl oxidase (LOX) and reactive oxygen species (ROS) accumulation." (PMID 32046347, 2020).
endometrioid ovarian carcinoma (2 papers, 2020 to 2021). "When considering endometrioid ovarian carcinoma patients, the mRNA expression levels of LOX, LOXL1, LOXL2, LOXL3, and LOXL4 demonstrated no relation with OS or PFS." (PMID 33058284, 2020). "Two genes, LOX and THBS1, did show correlation with a positive clinical outcome in endometrioid ovarian cancer despite a lack of significance between the high and low expression levels." (PMID 34868914, 2021).
hepatic echinococcosis (2 papers, 2022 to 2025). "AA is metabolized through COX, LOX, and CYP450 pathways to produce inflammatory mediators like PGE2 and leukotrienes (LTs), which can exacerbate inflammation and tissue damage in hepatic echinococcosis." (PMID 40921168, 2025).
Hernia (2 papers, 2025). "A multi-cohort analysis identified susceptibility loci near ELN, FBLN5, and LOX, genes that govern elastic-fiber assembly and collagen cross-linking, confirming that hernia risk aggregates with loci mediating ECM homeostasis." (PMID 41440470, 2025). "Functional studies show that LOX deficiency or polymorphism reduces cross-link density, weakening connective tissue and promoting aneurysm formation in vascular models—a mechanistic parallel to fascial attenuation in hernia." (PMID 41440470, 2025). "In the present work, we evaluated plasma concentrations of metalloproteinases (MMPs) and lysyl oxidase (LOX), enzymes involved in collagen metabolism, and peptides produced during collagen biosynthesis (PINP, PIIINP, and PIVNP) as potential biomarkers for the estimation of hernia risk." (PMID 40806165, 2025).
infarct (2 papers, 2018 to 2021). "Our results may simply indicate that the amount of LOX normally present in the cardiac tissue is sufficient enough to assure scar formation after infarction, and that a marked increase in its levels, as occurs in our transgenic model, does not have any additional influence." (PMID 35052579, 2021). "Our data evidence that, although LOX transgenesis induces baseline myocardial oxidative stress, neither ROS production, infarct size, nor post-infarction cardiac remodeling were exacerbated following myocardial ischemia-reperfusion." (PMID 35052579, 2021).
leukemia (2 papers, 2015 to 2024). A malignant (clonal) hematologic disorder, involving hematopoietic stem cells and characterized by the presence of primitive or atypical myeloid or lymphoid cells in the bone marrow and the blood. "The increased marrow stiffness could play a role in leukemia progression and could potentially be targeted with compounds which modify the expression and activity of enzymes such as lysyl oxidase, which regulate extracellular matrix (ECM) remodeling and degradation." (PMID 25962143, 2015).
liver cirrhosis (2 papers, 2019 to 2024). "LOXL1, a member of the lysyl oxidase (LOX) family of enzymes involved in collagen and elastin crosslinking, has also been linked to liver cirrhosis." (PMID 38565287, 2024).
lung disease (2 papers, 2017 to 2020). "In summary, our study provides a comprehensive analysis of the LOX/L family in fibrotic lung disease and indicates prominent roles for LOXL2/3 in fibroblast activation and LOX/LOXL2 in IPF." (PMID 28273952, 2017).
metastatic colorectal cancer (2 papers, 2019 to 2020). "Antibody targeting of LOXL2, which is the other member of the lysyl oxidase family that is highly expressed in NSCLC, have yielded disappointing results in clinical trials in pancreatic and metastatic colorectal cancer but, like LOX inhibitors, may yet prove effective in NSCLC treatment." (PMID 33014869, 2020).
muscular dystrophies (2 papers, 2021 to 2024). "LOX has been proposed to play a similar “double-edged sword” role in muscular dystrophies, including Duchenne muscular dystrophy (DMD), where increased LOX expression is associated with a fibrotic phenotype, but also appears to modulate cell differentiation in both in vitro and in vivo models." (PMID 39766266, 2024). "LOX gene is involved in fibrogenesis, as well as collagen and elastin cross-linking, it is observed that its expression level is increased in mice and dogs with muscular dystrophy, therefore, LOX, as well as ELN gene may be positively correlated with patients with BMD." (PMID 34922439, 2021).
Myocardial Diseases (2 papers, 2019 to 2020). "LOX plays a crucial role in the maintenance of extracellular matrix stability and could participate in cardiac remodeling associated with the pathogenesis of myocardial diseases." (PMID 32046347, 2020).
myocardial ischemia (2 papers, 2021 to 2022). A disorder of cardiac function caused by insufficient blood flow to the muscle tissue of the heart. "As infarct size is a major determinant of cardiac remodeling and scar formation, here, we first assessed the effect of LOX on acute myocardial ischemia-reperfusion injury in isolated hearts from a transgenic mouse model that over-expresses LOX in the myocardium." (PMID 35052579, 2021). "After long-term myocardial ischemia (28 days after injury), the expression of fibrotic genes (e.g., COL1A1 and LOX) was dramatically enhanced, leading to increased ECM production and deposition, as revealed by immunostaining of type I collagen." (PMID 36089604, 2022). "However, in using this approach, we demonstrated that human LOX over-expression does not modify acute myocardial ischemia-reperfusion injury, as no changes were observed in either infarct size, determined by triphenyltetrazolium staining, LDH release, or functional recovery." (PMID 35052579, 2021).
nasopharyngeal carcinoma (2 papers, 2016 to 2019). A carcinoma arising from the nasopharyngeal epithelium. "To evaluate the prognostic value of LOX levels in primary nasopharyngeal carcinoma, we performed an immunohistochemical analysis using 233 tissue biopsy specimens from as many patients." (PMID 26882568, 2016). "Higher LOX expression was also an independent predictor of poor prognosis in patients with nasopharyngeal carcinoma." (PMID 26882568, 2016). "However, the contribution made by LOX to the progression of nasopharyngeal carcinoma (NPC) has not been examined previously." (PMID 26882568, 2016).
Nephropathy (2 papers, 2021 to 2022). A nonspecific term referring to disease or damage of the kidneys. "It has shown that inhibition of lysyl oxidase can reduce the progressive nephropathy and oxidative stress caused by CsA administration, thereby reducing the side effects of CsA25." (PMID 35730865, 2022). "In the present study, we demonstrated that CsA- induced nephropathy is associated with LOX and LOXL2 overexpression in the kidney." (PMID 34127702, 2021). "Compared to animals with CsA nephropathy that were treated with the vehicle control, those treated with pan-LOX and LOXL2 inhibitors showed significant reductions in the protein expression of α-SMA (P < 0.05), suggesting reduced myofibroblast activation." (PMID 34127702, 2021). "Collectively, our study suggests that Pan-LOX and LOXL2 inhibition can attenuate progressive nephropathy due to CsA administration." (PMID 34127702, 2021).
osteoarthritis (2 papers, 2018 to 2022). A noninflammatory degenerative joint disease occurring chiefly in older persons, characterized by degeneration of the articular cartilage, hypertrophy of bone at the margins and changes in the synovial membrane. "Human lysyl oxidase (LOX) is a hypoxia response gene whose product can catalyze collagen cross-linking, while HIF-2α can upregulate LOX and play a crucial role in osteoarthritis." (PMID 36503684, 2022). "The product of the lysyl oxidase (LOX) gene, a hypoxia-responsive gene, catalyzes collagen crosslinking and is thought to be important in cancer metastasis and osteoarthritis." (PMID 29955245, 2018).
pancreatic adenocarcinoma (2 papers, 2017 to 2021). "Finally, LOX inhibition in transgenic mice developing pancreatic adenocarcinoma prolongs tumor‐free survival and is associated with decreased fibrillar collagen and increased infiltration of macrophages and neutrophils." (PMID 27974353, 2017).
pelvic organ prolapse (2 papers, 2020 to 2022). Abnormal descent of a pelvic organ resulting in the protrusion of the organ beyond its normal anatomical confines. "Several studies have investigated the role of LOX in normal elastogenesis, as well as LOX-associated anomalies and pelvic organ prolapse." (PMID 32953891, 2020).
polycystic ovary syndrome (2 papers, 2016 to 2020). A disorder that manifests as multiple cysts on the ovaries. "High levels of AGEs have also been shown to stimulate LOX activity and subsequent collagen deposition in ovarian tissues of patients with polycystic ovary syndrome (PCOS)." (PMID 28036074, 2016). "The pro-inflammatory Interleukin 1β (IL-1β) contributes to LOX overexpression in polycystic ovary syndrome (PCOS), with increased LOX and IL-1β levels being observed in granulosa cells and follicular fluid of PCOS patients." (PMID 32708046, 2020).